ERBB2 (erb-b2 receptor tyrosine kinase 2)
Diseases named in the same sentence as ERBB2 in open-access papers (continued):
Sharing a sentence is not in itself a finding about the gene and the disease.
tumor (continued). "The dramatically increased BTC‐mediated tumor burden was EGFR‐dependent, but also ERBB4 and ERBB2 were involved in PDAC development or progression, as depletion of EGFR, ERBB2, or ERBB4 significantly improved the survival rate of BTC‐mediated PDAC." (PMID 32335999, 2020). "In our study, almost 19% of the PDAC patients showed ERBB2/Her2-neu amplification, whereas 30% of the PAC patients showed ERBB2/Her2-neu amplification in the tumour." (PMID 32552660, 2020). "In the primary tumor, 15 (35.7%), 11 (26.2%), 4 (9.5%) and 4 (9.5%) patients harbored amplifications in all 3 exons of MYC, CCND1, ERBB2 and CCNE1, respectively." (PMID 33298978, 2020). "For those intermediate tumours of a 2+ score, fluorescence in situ hybridisation (FISH) is employed to assess ErbB2 gene amplification." (PMID 33245725, 2020). "Curcumin also downregulated the expression of the AR protein and NKX3.1 tumor suppressor, as well as PSA levels, Erb-B2 Receptor Tyrosine Kinase 2 (ERBB2), and epidermal growth factor receptor (EGFR)." (PMID 33182828, 2020). "In a mouse model of ErbB2-driven metastatic breast cancer, THC treatment was able to reduce tumor growth, as well as the amount and severity of lung metastases." (PMID 32708138, 2020). "Evaluating the same 47 gene sets at the time of surgery compared to pre-treatment by GSEA, reductions in proliferation, ERBB2 signaling, and ESR1 signaling were observed, consistent with lower tumor content." (PMID 33203854, 2020). "The main supply of production in mice was found to be the tumor-infiltrating CD4+ FoxP3+ regulatory lymphocytes, which increased in ERBB2-positive tumors." (PMID 33066388, 2020). "To determine the proportion of ERBB2-high tumors across the HER2 IHC groups, we analyzed a retrospective dataset of 392 tumor samples from HCB with both HER2 IHC status and gene expression data." (PMID 32674482, 2020). "We performed ISH to confirm the results of ERBB2, FGFR1, and FGFR2 status in the two lesions, and we confirmed amplification in either tumour #1 or tumour #2." (PMID 31929516, 2020). "In support of the tumor suppressive role of miR-338-3p, it has been reported that SOX9 regulates ERBB2 expression in PDA." (PMID 32552862, 2020). "They found that “dual-targeted” T cells kill ErbB2+ tumor cells efficiently, but their proliferation requires coincubation with the target cells with both Tn-MUC1 and ErbB2 expression." (PMID 32194541, 2020). "Only partial tumor growth inhibition was achieved in WT CIK cell-treated mice, while the in vivo antitumor functions of ERBB2-CAR CIK cells resulted in complete elimination of human alveolar RMS in the setting of preemptive therapy." (PMID 33193388, 2020). "A novel molecular pathway for BC tumorigenesis in ER-negative/ERBB2-positive and RANK-expressing BC tumor cells has also been proposed." (PMID 33066388, 2020). "Kwak et al3 reported patient cases of MET and ERBB2 coamplification occurring in the same tumor cells, including a single case of MET, ERBB2, and EGFR coamplification all occurring within a single tumor cell population." (PMID 32338752, 2020). "A patient with metastatic colon cancer received an infusion of CAR T cells targeted to the antigen HER2 (ERBB2) and died 5 days later due to the massive on-target/off-tumor toxicity of the CAR T cells for lung cells that express low levels of HER2." (PMID 33101285, 2020). "Among the potential drug targets, we identified some well-known targets, including EGFR, ERBB2, and PARP1 as well as CDK2 and CDK4/6, which are related to the regulation of tumor cells development." (PMID 33287876, 2020). "As a typical receptor tyrosine kinase (RTK), activation of erbB2 induces signal transduction in a number of pathways, including PI3K/Akt, MAPK/Erk, and mTOR signaling cascades, involved in tumor cell proliferation and survival." (PMID 32353937, 2020).
tumor (continued). "Generally, therapeutic decisions are based on tumour histology and receptor status: ER (Estrogen Receptor), PR (Progesterone Receptor) and ERBB2, also known as HER2 (Human Epidermal Growth Factor Receptor 2), in tumour tissue biopsies." (PMID 33051521, 2020). "This group of patients had higher tumor volume and stage and percentage of cases with bone metastases than the group with PSA high/Ki67 low, as well as significantly increased levels of ErbB2 and hyaluronic acid." (PMID 30980038, 2019). "All tumors were analyzed using an NGS multi-gene panel that expands the tumor genetic portrait, including genes such as BRAF, ERBB2, KRAS, and MET in addition to EGFR and ALK/ROS1, in accordance with recently updated recommendations." (PMID 30669267, 2019). "The prognosis and treatment depend on the stage of the disease at diagnosis, the type of tumor, the grade, the proliferation status (Ki67 expression), and the expression of HER2/ERBB2 and the hormonal receptors, estrogen and progesterone receptors." (PMID 31442252, 2019). "Gains of oncogenes including EGFR (7p12), ERBB2 (17q12), KRAS in the EGFR pathway were characteristic for LUAD and contribute to cell proliferation and tumor development, suggesting this is a core requirement for LUAD pathogenesis." (PMID 31448219, 2019). "For example, the highest levels of pEGF-R, ErbB2, pAkt, and Erg as a marker for TRMPSS2-ERG fusion gene were found in the tumor epithelium of this group." (PMID 30980038, 2019). "Its tumor-suppressor function depends on the repression of at least three gene targets, namely: c-MYC, COX2 and ERBB2." (PMID 31416219, 2019). "ERBB2 amplification and 4q34.3 deletion were specially identified in LUAD patients who had tumor recurrence occurring within 3 years after therapy." (PMID 31448219, 2019). "The ERBB2 amplification was validated in primary omentum tissue using SNP genotype–based CNA detection and in the tumor tissue sample from interval debulking surgery with in situ hybridization and IHC." (PMID 32914024, 2019). "Alcohol administration increased STARD10, ERBB2 and p-ERK protein levels by 6.8-, 4.8- and 1.5-fold compared to control tumor tissues." (PMID 30611309, 2019). "The three key proteins identified by our decision tree are strongly associated with important clinical parameters, namely ER status (INPP4B), tumor grade (CDK1), and HER2 status (ERBB2)." (PMID 31315058, 2019). "For EGFR, ERBB2, and MET gene amplification, we set the absolute copy number ≥6 as amplification for WES with tumor and normal pairs and log2 ratio ≥ 3-fold standard derivation (SD) as amplification for the ctDNA compared with a panel of normals." (PMID 31739500, 2019). "Further to this, XAGE3, S100P, CSH1, ErbB2, PAPPA1, EGLF6, COBLL1 were all identified as having potential roles in growth and development, whilst XAGE3, ErbB2, PAPPA1, EGLF6 have reported links to tumour growth." (PMID 31533811, 2019). "In multivariable analysis in the ESR1+/ERBB2- set the MKI67 status and tumor stage displayed almost identical hazard ratios, however only stage was clearly significant." (PMID 31307414, 2019).
tumor (continued). "This analysis confirmed the connection of INPP4B with ER status, CDK1 with tumor grade, and ERBB2 with HER2 status." (PMID 31315058, 2019). "We also present data suggesting that the combination of anti-ERBB-2 agents and RANKL inhibitors have a potential direct anti-tumor effect and should be further tested in certain BC patients." (PMID 31796128, 2019). "In proto-oncogenic proteins erbB-2, MET and FGFR, the enhanced and gain-of-carcinogenic effects by multimerization are also observed in tumor growth and cancer progression." (PMID 31439836, 2019). "More recently FOXP3 has emerged as a tumour suppressor in breast and prostate epithelia, repressing a number of oncogenes including c-myc, Ezh2, HER-2/ErbB2 SKP2 and SATB1, while up regulating expression of tumour suppressors p21 and LATS2." (PMID 29963231, 2018). "Nonetheless, its addition to CD3ζ in a second generation ErbB2-specific NK-92 CAR led to improved function compared to a CD3ζ construct alone and was similar to that of CD137-CD3ζ CAR against ErbB2-expressing tumor cells." (PMID 29497427, 2018). "Interrogation of BRD4-amplified HGSOC TCGA data revealed an enriched ERBB2 signature, consistent with activated NRG1 signaling in this tumor subset." (PMID 30036377, 2018). "We compared the expression status of ESR1 and ERBB2 in DTCs with the clinical ER and HER2 status of the corresponding primary tumor." (PMID 30211312, 2018). "To determine whether Kindlin-3 expression may reflect the amount of tumor infiltrating leukocytes (TILs) we analyzed the mRNA levels of different immune markers in the same series of tumors and found that triple negative and ERBB2 tumors presented the highest levels of CD45, CD86, CD28 and CD4." (PMID 30477537, 2018). "In particular, tumor cell-specific antibodies such as anti-CD20 (rituximab) and anti-erbB2/neu (trastuzumab) antibodies have proven to be effective in clinical cancer treatment." (PMID 29423071, 2018). "Studies beyond the scope of the present manuscript will be required to understand the relative roles of ERBB2 and mutant RAS proteins in protecting tumor cells from [neratinib + valproate]." (PMID 29464055, 2018). "Overexpression of cytoplasmic ERBB2 plays an important role in the progression of CRC, where its expression correlates with the tumor size, subserosal invasion, liver metastasis, and Dukes’ classification." (PMID 29740162, 2018). "Routine screening of HER2 overexpression or ERBB2 amplification is therefore recommended for breast and oesogastric adenocarcinomas on the tumor sample used for the diagnosis." (PMID 29515767, 2018). "Among these, ERBB2, PTPRD, PTPRT, AURKB also correlated with node status, stage, tumor size and/or presence of metastasis." (PMID 29844865, 2018). "Activation of the NTSR1 receptor leads to activation of the EGFR family: in particular EGFR, ErbB2/HER2, and ErbB3/HER3, which in turn are responsible for signal transduction within the tumor cell." (PMID 29467963, 2018). "Tumor cell content, DCIS content, HER2 immunohistochemical score of the invasive tumor and the DCIS, as well as relative expression of the mRNA markers ERBB2, ESR1, PGR and MKI67 and absolute Δ40-ddCq values are shown." (PMID 30342538, 2018). "When examining consistently altered pathways or kinases across more than one platform, the GNRH, PTEN, STAT3, IL-8, B cell receptor, NF-kB and NO-ROS in macrophages pathways as well as the kinases ERBB2, ERBB3 and SYK were upregulated in tumor tissue." (PMID 28423512, 2017). "When animals that had rejected the initial tumor and the first rechallenge with GL261/ErbB2 were injected once again with GL261/ErbB2 cells but this time after depletion of CD4+ and CD8+ T cells, tumors formed in a large proportion of the mice." (PMID 28572802, 2017).
tumor (continued). "Examining the very high expressing cases (with Tumor Cell Score ≥ 2.5, indicating high protein expression throughout the tumor), EGFR+ERBB2 expression was only observed in one GU tumor, while two UroA tumors expressed both EGFR and ERBB3 at high levels." (PMID 28388586, 2017). "In contrast, ErbB2-CAR CIK cells specifically recognized and rapidly killed their tumor targets within a few hours." (PMID 29029499, 2017). "Tumors were classified according to the primary tumor TNM stage, histological type, grade, and presence of estrogen receptor (ER), progesterone receptor (PR), and ERBB2 (HER2) amplification." (PMID 28810143, 2017). "The top 10 unpaired normal (n=4 samples) to tumor (n=11 samples) increased protein kinases were SYK, ZAP70, ARG (ABL2), ERBB3, ABL, TEC, MER (MERTK), AXL, EGFR and ERBB2." (PMID 28423512, 2017). "Due to its ability to interfere with tyrosine-phosphorylation of ErbB2 and ErbB3, EGCG further inhibited downstream MAPK cascade, leading to the reduction in tumor growth." (PMID 28286519, 2017). "In contrast, ErbB2-CAR CIK cells specifically recognized, separated and rapidly killed their tumor targets." (PMID 29029499, 2017). "Here, we demonstrate a potential cell therapeutic approach using ErbB2-CAR-CIK cells for the recognition and elimination of tumor cells expressing ErbB2, which we identified as a targetable antigen on high-risk STS cells." (PMID 29029499, 2017). "The inhibition of HSP90 by 17-AAG depletes ErbB2, EGFR, phosphorylated AKT, and other oncogenic proteins involved in tumor progression." (PMID 29097911, 2017). "Although it is known that the immediate target of lapatinib is the ATP-binding pocket of ErbB2 and EGFR kinase domains, it has been demonstrated that modulation of specific intracellular targets can enhance or block lapatinib-induced anti-tumor activities." (PMID 28938602, 2017). "The ErbB family of RTKs, which consist of Epidermal growth factor receptor (EGFR) (ErbB1 or HER1), ErbB2 (HER2 or Neu), ErbB3 (HER3), and ErbB4 (HER4), have been shown to promote tumor progression in various cancer types." (PMID 27902463, 2017). "In contrast, ErbB2-CAR CIK cells demonstrated significantly increased cytolytic potential against ErbB2-expressing target cells, including primary tumor cells." (PMID 29029499, 2017). "Expression of therapeutic target genes such as ER (ESR1) and HER2 (ERBB2) also varied across and within tumours." (PMID 28474673, 2017). "Inhibitors targeting the ErbB2 selective tyrosine kinase and combined blockade of PI3K/AKT and MAPK pathways inhibit tumor growth including RCC." (PMID 29050225, 2017). "Overall, these data demonstrate that lapatinib decreases tumor latency and mammary gland morphogenesis by negatively regulating the EGFR/erbB-2 and ERα signaling pathways." (PMID 28061785, 2017). "Notably, we found mutations of ERBB2 in four tumours lacking ERBB2 amplification, suggesting that more patients may benefit from ERBB2-directed therapy." (PMID 28052061, 2017). "In the present work, we show that the monoclonal antibodies against the ErbB2/HER2 receptor Trastuzumab and Pertuzumab can be biotinylated and that when they are used in combination with AvidinOX, exhibit increased anti-tumor activity." (PMID 28186982, 2017). "We performed immunostaining of EGFR, ASAP1, ERBB2, ERBB4 and β-catenin in HBL tumor tissue from an expanded cohort of children treated with liver transplantation (n = 19) or with surgical resection (n = 40) and biopsy (n = 1)." (PMID 27910913, 2016).
tumor (continued). "Under parous (p) and nulliparous (np) conditions, median time to tumor formation (MTTF) was similar for both ErbB2 (p = 214 and np = 244 days) and ErbB2/IRS2 bigenic mice (p = 211 and np = 264 days)." (PMID 27765041, 2016). "The expression of GLI1, Shh and NF-κB correlated with clinico-pathological variables including histological type, tumor grade, tumor size, lymph node metastasis, and EGFR, ErbB2, estrogen receptor (ER) and progesterone receptor (PR) expression." (PMID 26843616, 2016). "Several of these genes can also be considered as marker of tumor differentiation or contribute to epithelial-to-mesenchymal transition (EMT) such as CDH1, EDN1 or ERBB2 for instance." (PMID 27509260, 2016). "ERBB2 and ERBB3 dimerization triggers the activation of survival and growth signaling cascades, such as through PI3K and MAPK kinases, in both normal and tumor cells." (PMID 27626312, 2016). "Second, ERBB2 CN assessment by ISH is limited to what is feasible to count, but MIP pools ten thousands of tumor cells and has the power to objectify or rectify prior IHC/ISH test result." (PMID 27716627, 2016). "Here the authors report that ERBB2 induces indirect phosphorylation of TOM1L1 that promotes trafficking of the metalloprotease MT1-MMP to invadopodia, which leads to tumour cell invasion." (PMID 26899482, 2016). "Alcohol increased the phosphorylation of ErbB2 and p38γ MAPK which was revealed by the immunofluorescent staining of fixed tumor tissues." (PMID 27416801, 2016). "The dimers stimulate ErbB2 phosphorylation, initiate downstream signaling events including PI3K/AKT and MAPK/ERK pathways, and culminate in tumor growth." (PMID 27564098, 2016). "The comparison of ERBB2 expression on CTC and tumor tissue resulted in an overall concordance of 74% and 89% when comparing CTC with the primary tumor and 69% when compared to metastases, respectively." (PMID 27223437, 2016). "Traditionally, treatment decisions have been based on tumor histology and three receptor biomarkers including ER (estrogen receptor 1), PR (progesterone receptor), and HER2 (erb-b2 receptor tyrosine kinase 2)." (PMID 27150055, 2016). "In this model, we observed a significant delay in tumor onset in the compound transgenic mice expressing both mda-7/IL-24 and Erbb2 transgenes as compared to the MMTV-Erbb2 littermate controls." (PMID 26474456, 2015). "Our third strategy was to co-express both a tumor promoting gene, Erbb2, and MDA-7/IL-24 endogenously in the mammary gland, and to follow tumor progression." (PMID 26474456, 2015). "The PAM50 qRT-PCR assay was used to: a) assess tumor gene expression levels for ESR1, PGR, ERBB2, and 10 proliferation genes and b) classify tumors into intrinsic subtype (Luminal A, Luminal B, Basal-like, HER2-enriched, Normal-like)." (PMID 25884832, 2015). "ERBB2/HER2 belongs to the EGFR-family of receptor tyrosine kinases and its overexpression can promote tumor progression." (PMID 25596742, 2015). "Reverse phase microarray proteomic analysis revealed ErbB2/3 and downstream members of the PI3K/AKT and MAPK/ERK pathways as well as PTEN to be protein targets differentially expressed in the M12 tumor cell compared to its parental p69 cell." (PMID 26544868, 2015). "We show that this method can detect BRCA1, BRCA2, ERBB2 and CCNE1 copy number changes in DNA extracted from snap-frozen and FFPE tumour tissue, with 100% sensitivity and >99.5% specificity." (PMID 26569395, 2015). "Using PDAC datasets of the NCBI Gene Expression Omnibus (GEO, GSE28735) database, ErbB2, hCNT1, hCNT3, ABCG2, MRP1 and MRP2 mRNA expression was measured in 45 tumors (T) and adjacent non tumor tissues (ANT)." (PMID 25890497, 2015). "Concerning the genes related to tumor progression, we found HSP90AB1, GRB2, ERBB2/3, EIF4A3, HDGF, and CSNK2B." (PMID 25625699, 2015).